GRM3 (glutamate metabotropic receptor 3)
Diseases named in the same sentence as GRM3 in open-access papers (continued):
Sharing a sentence is not in itself a finding about the gene and the disease.
schizophrenia (continued). "Physiological roles of GRM3 in brain functions and its functional roles in the pathogenesis of schizophrenia remain to be resolved." (PMID 24758191, 2014). "In schizophrenia, for example, allelic variation in GRM3 (the gene encoding mGlu3) has been associated with disease risk, and mGlu2/3 agonists have shown efficacy in models of the disorder, and in one study, of the disorder itself." (PMID 24053122, 2013). "Like Grm3, Nrg3 (neuregulin 3) is a highly connected gene in ErGeN3 as well as a schizophrenia candidate gene." (PMID 22511924, 2012). "But the hypogyric subgroup exhibited a higher than expected presence of the schizophrenia-risk SNVs of GRIN2A (rs9940680 and rs1420040) and lower rate of the protective variant of GRM3 (s14513928; a lower rate of this protective variant is also notable in healthy siblings)." (PMID 37158213, 2023). "These signaling mechanisms appear to have direct relevance to human cognition, as genetic insults to mGluR3 (GRM3) are a risk factor for schizophrenia, and a genetic alteration that increases GCPII production and lowers mGluR3 signaling is associated with inefficient dlPFC activity and lower IQ." (PMID 34312496, 2022). "In addition, the expression of GRM3 was significantly reduced in undifferentiated schizophrenia, while it was increased in disorganized and paranoid schizophrenia." (PMID 28809853, 2017). "The schizophrenia data show that involvement of GRM3 in the disorder and its genetic risk architecture is not reflected in total membrane mGlu3 immunoreactivity in superior temporal cortex." (PMID 27130562, 2016). "In sum, our results agree with several previous studies and do not support GRM3 as a susceptibility gene for schizophrenia." (PMID 24498053, 2014). "We found that GRM3 polymorphisms modulate the susceptibility to HD but do not significantly influence the risk of schizophrenia or depression." (PMID 24498053, 2014). "To explore the physiological roles of GRM3 in brain functions and its functional roles in the pathogenesis of schizophrenia, we generated Grm3 knockout (KO) mice and conducted comprehensive behavior tests, electrophysiological, and pharmaco-physiological analyses." (PMID 24758191, 2014). "We found that GRM3 polymorphisms modulate the susceptibility to HD but do not significantly influence the risk for schizophrenia or depression." (PMID 24498053, 2014). "Our data indicated that GRM3 polymorphisms do not contribute to genetic susceptibility to schizophrenia and depression, but they confer an increased risk of HD in a Chinese population." (PMID 24498053, 2014). "Examination of our own data and those of other groups leads us to conclude that at present, GRM3 should not be viewed as a gene for which there is replicated evidence for association with schizophrenia." (PMID 15892884, 2005). "Thus, although promising clinical trial evidence that mGlu2/3 agonism is an effective antipsychotic strategy has not been confirmed, there remains considerable interest in the mechanisms by which GRM3/mGlu3 may contribute to schizophrenia and its treatment." (PMID 28655286, 2017). "The co-morbidity of schizophrenia and SCRD may in part stem from dysfunction in common brain mechanisms, which include the glutamate system, and in particular, the group II metabotropic glutamate receptors mGlu2 and mGlu3 (encoded by the genes Grm2 and Grm3)." (PMID 25950516, 2015). "Seventeen SNPs throughout the GRM3 gene were genotyped using MALDI-TOF within the MassARRAY system, and the allele and genotype distributions were compared between 619 healthy controls and 433 patients with schizophrenia, 409 patients with major depression, and 584 unrelated addicts." (PMID 24498053, 2014). "However, given the moderate level of linkage disequilibrium across this gene, both this study and other current data are insufficient to rule out the possibility that GRM3 is a true susceptibility gene for schizophrenia." (PMID 15892884, 2005).
schizophrenia (continued). "While the current data concerning GRM3 do not allow rejection of the null hypothesis, they are insufficient to rule out the possibility of GRM3 as a true susceptibility gene for schizophrenia." (PMID 15892884, 2005). "The differences between the siblings and HC were seen in GRM3 and CACNA1C, and the differences between the siblings and schizophrenia were limited to CACNA1C." (PMID 37158213, 2023). "We examined the association of 39 single nucleotide polymorphisms in eight genes (GRIN2A, GRIN2B, SLC1A2, SLC1A3, SLC17A7, GRM3, GRM7, and GRM8) involved in the glutamatergic system with the development of clinical heterogeneity of schizophrenia." (PMID 36980845, 2023). "Therefore, the mechanism underlying the association between GRM3 and schizophrenia is not clear." (PMID 27242534, 2016). "Our data do not support the hypothesis that variation in GRM3 is associated with schizophrenia." (PMID 15892884, 2005). "Multiple differentially expressed genes (KCNIP4, GRM3, PRKG1, NPY for inh-C, and TRPC3 for inh-CCK) were related to glutamate reception and calcium channel activity, indicating these processes are altered within inhibitory midbrain neurons in schizophrenia." (PMID 39397771, 2025). "Metabotropic glutamate receptor 3 (mGluR3), encoded by the GRM3 gene, modulates glutamate neurotransmission through NMDAR, which are implicated in cognition and negative symptoms in schizophrenia." (PMID 40943517, 2025). "These experiments indicate that mGlu3Δ4 may negatively modulate mGlu3, and thereby impact on the roles of GRM3/mGlu3 in schizophrenia and as a therapeutic target." (PMID 28655286, 2017). "Finally, a SNP within the NMDAR GRIN2A subunit gene is now genome-wide significant for schizophrenia, as are SNPs at the loci for GRIA1, GRM3 and SRR, all of which impact on NMDAR signalling." (PMID 25315827, 2015). "Genetic studies from schizophrenia also suggest that α 7 nicotinic cholinergic receptor, catechol-O-methytransferase (COMT) and GRM3 genetic variation may be related to the presence of neurological soft signs." (PMID 21827719, 2011). "Resequencing of all exons and splice sites of GRM3 of schizophrenia patients revealed no missense or splice-site SNPs, suggesting that intronic SNPs located in GRM3 or related haplotypes may affect subtle regulatory effects on GRM3 transcription." (PMID 24758191, 2014). "Moreover, GRM3 genotype modulates prefrontal BOLD signals and N-Acetylaspartate (NAA) levels and mGlu3 protein levels were reduced in the prefrontal cortex in postmortem brains of schizophrenia." (PMID 22022368, 2011). "Thus, mGlu3Δ4 appears to serve as a negative modulator of mGlu3, and in this way the GRM3Δ4 isoform may contribute to the mechanism by which allelic variation in GRM3 is associated with schizophrenia risk." (PMID 28655286, 2017). "The glutamate metabotropic receptor 3 (GRM3) gene has been widely investigated since it modulates signaling through NMDA receptors which are a relevant contributor to the cognitive and negative symptoms of schizophrenia." (PMID 31040787, 2019).
melanoma (16 papers, 2013 to 2024). A malignant, usually aggressive tumor composed of atypical, neoplastic melanocytes. "Exon capture sequencing of 734 GPCRs in malignant melanoma showed that a third glutamate receptor, GRM3, is frequently mutated in human melanoma." (PMID 35158973, 2022). "The identification and characterization of the mutational hotspot p.Glu870Lys in GRM3 suggests its functional importance in melanoma tumorigenesis." (PMID 36139432, 2022). "GRM3 is reported frequently mutated in melanoma, a common form of skin cancer, and mutated GRM3 increased cellular migration." (PMID 28615627, 2017). "Mutated GRM3 was shown to contribute to the proliferation and invasiveness of melanoma cells in vitro and induce an increased phosphorylation of MEK." (PMID 24743024, 2014). "Specifically, out of 23 nonsynonymous mutations from GRM genes, one nonsense and four missense mutations were from GRM3, previously shown to harbor activating mutations in melanomas." (PMID 25393105, 2014). "Exon 1 of the TRRAP gene and exons 1, 2, 3, 4 and 5 of the GRM3 gene were analyzed as these exons have also been reported to harbor somatic mutations in melanoma." (PMID 24137342, 2013). "Combining these previous findings with our results, we considered that mutations in GRM3 may also play a key promotor in high TMB to increase the potential of response to ICIs in melanoma." (PMID 32969604, 2020). "Further studies will need to address whether mutations of GRM3 or GRIN2A are the reason for tumorigenicity or aggressiveness in melanoma cells." (PMID 28522871, 2017). "TRRAP and GRM3 were also found to be mutated in a small proportion of tumors, indicating that the glutamate pathway might play an important role in melanoma development and progression." (PMID 25393105, 2014). "Four of the mutations in these genes, GRM3 p.D548N, GRM3 p.R668H, NF1 p.W336T, and NF1 p.P1851S, have been reported previously in COSMIC and/or TCGA studies of melanoma." (PMID 30312528, 2019). "Even though riluzole was shown to inhibit growth of cell lines expressing GRM1, a clinical trial is ongoing to explore the antitumor activity of riluzole in melanoma without prior analysis of GRM3 status." (PMID 24743024, 2014). "GRM3 and GRIN2A/2B alterations were also frequently observed in the tumors sequenced herein, suggesting the importance of glutamate mediated transduction in melanoma." (PMID 25393105, 2014). "The ionotropic glutamate receptor GRIN2A and the metabotropic glutamate receptor GRM3 were found to be mutated in 25% and 16%, respectively, of melanoma samples, but without recurrent mutations for GRIN2A and with only a small percentage of recurrent GRM3 mutations." (PMID 30987166, 2019).
cognitive deficits (12 papers, 2017 to 2025). "Results suggest that Grm3, expressed in ExN9 and ExN10, plays a specific role in long-term depression and neuroprotection, and potentially be involved in cognitive impairment." (PMID 39635132, 2024).
breast carcinoma (10 papers, 2017 to 2024). "This extracellular glutamate then activates the GRM3 metabotropic glutamate receptor to drive receptor recycling leading to basement membrane disruption and invasion in breast cancer." (PMID 29269878, 2017). "Whether S100A4 and GRM3 can be utilized as therapeutic targets for bone metastasis from breast cancer is worth further pursuit." (PMID 28615627, 2017). "Suppression of miR-374c-5p, in turn, promoted proliferation, migration, and invasion of cells by activating glutamate metabotropic receptor 3 (GRM3) expression, which is a glutamate receptor modulating glutamate processing and has been shown to drive breast cancer cell metastasis." (PMID 36497250, 2022).
depression (10 papers, 2009 to 2024). "If GRM3 is a true susceptibility gene for depression, its effect on the disease risk is weak or the susceptibility alleles are only in weak LD with the markers we tested." (PMID 24498053, 2014). "Only one GRM3 SNP was analyzed in their study; therefore, further studies analyzing multiple loci should be performed to replicate their findings and evaluate the effects of other variations of GRM3 on the risk of depression." (PMID 24498053, 2014). "Thus, the current data do not provide significant support for the hypothesis that GRM3 is a susceptibility gene for depression." (PMID 24498053, 2014). "The metabotropic glutamate receptor 3 (GRM3), a member of the group II family of mGlus, is coupled to second message pathways via GTP-binding proteins and is involved in presynaptic depression by decreasing the evoked release of glutamate." (PMID 22909248, 2012). "Supporting the feasibility of future exploration of Grm3 inhibition in glioma patients, a similar negative allosteric modulator of Grm2/3 (decoglurant) was well tolerated by patients treated in a phase II clinical trial of major depressive disorder (ClinicalTrials.gov: NCT01457677)." (PMID 33575479, 2021). "Also noteworthy, the glutamate receptor metabotropic 3 (GRM3) was consistently down-regulated among the suicides with and without major depression in two areas of the prefrontal cortex BA46 and BA47 and in two areas of the parietal cortex BA38 and BA20." (PMID 19668376, 2009).
epilepsy (9 papers, 2017 to 2025). A brain disorder characterized by episodes of abnormally increased neuronal discharge resulting in transient episodes of sensory or motor neurological dysfunction, or psychic dysfunction. "Intriguingly, our findings suggested that GRM3 may be a potential risk gene for epilepsy." (PMID 34456681, 2021). "Several candidate genes for epilepsy include calmodulin-regulated spectrin-associated protein 1-like protein 1 (CAMSAP1L1), glutamate metabotropic receptor 3 (GRM3), CD3 gamma subunit of T-cell receptor complex (CD3G), and solute carrier organic anion transporter family member 3A1 (SLCO3A1)." (PMID 37246165, 2023). "These lines of evidence suggest that GRM3 may have a role in epilepsy." (PMID 34456681, 2021). "In epilepsy models, inhibition of the NAAG degradation enzyme (glutamate carboxypeptidase II) and GRM3 agonists module seizure frequency, and activation of GRM3 in traumatic brain injury models indicates a protective effect." (PMID 35587487, 2022). "Our study not only provides new insights into genetic architecture of epilepsy but also prioritizes potential molecular targets (including GRM3 and TTC21B) for development of new drugs and therapeutics for epilepsy." (PMID 34456681, 2021). "In conclusion, our study not only provides new insights into genetic architecture of epilepsy but also prioritizes potential molecular targets (including GRM3 and TNKS) for development of new drugs and therapeutics for epilepsy." (PMID 34456681, 2021).
glioblastoma (9 papers, 2018 to 2025). The most malignant astrocytic tumor (WHO grade IV). "Modulation of intracellular signaling cascades via activation of Grm3 has been implicated in resistance of glioblastoma to chemotherapy by maintaining the GSC phenotype." (PMID 33575479, 2021). "Of the eight known Grm subtypes, only GRM3 is expressed at high levels in glioblastoma (ANOVA, p < 0.001)." (PMID 33575479, 2021). "In glioblastoma cell culture models, Grm2 and Grm3 gene expression levels were also higher in primary cultures maintained under conditions that retain the GSC phenotype, as compared to long-term glioma cells cultured in serum-containing differentiation medium." (PMID 33575479, 2021). "We performed quantitative reverse-transcriptase polymerase chain reaction (qRT-PCR) of Grm3 and a panel of neuroglial differentiation markers in 482 single glioblastoma cells derived from six freshly dissociated patient tumors." (PMID 33575479, 2021). "Clinical exploration of Grm3 targeting in glioblastoma patients is warranted." (PMID 33575479, 2021). "In summary, Grm3 may be a novel, pharmacologically accessible target in glioblastomas, although future studies will be required to decipher the precise molecular mechanism of potential anti-glioma activity of Grm3 inhibitors." (PMID 33575479, 2021). "Predominant expression of GRM3 in proneural glioblastoma led us to explore whether GRM3 was indeed expressed at higher levels by GSCs." (PMID 33575479, 2021). "A negative association of GRM3 gene expression levels with overall survival of patients was confined to the proneural glioblastoma gene expression subtype (p = 0.039), which is associated with a more stem-like gene expression phenotype." (PMID 33575479, 2021). "In addition, GRM3 has also been shown to suppress colon cancer and glioblastoma growth." (PMID 40342962, 2025). "To sum up, we identified seven genes (GRIA1, GRIA2, GRIK1, GRIK4, GRM3, GLUL, BCAT1) whose mRNA expression may serve as potential molecular biomarker candidates to distinguish glioblastoma and brain metastases tissue derived from surgical resections." (PMID 38835368, 2024). "Of note, GRM3 is located on chromosome 7, which is commonly amplified in IDH wild-type glioblastoma, yet GRM3 copy number gains appear not to be associated with gene expression." (PMID 33575479, 2021). "These analyses support the heterogeneity of GRM3 gene expression among glioblastoma cells and support the notion of co-expression of GRM3 with other stem cell enrichment markers." (PMID 33575479, 2021). "We focused on CD133 to explore GRM3 expression in GSCs versus non-GSCs because the presence of the AC133 epitope of CD133 on the cell surface, but not CD133 gene expression, enriches for GSCs and is associated with the proneural glioblastoma subtype." (PMID 33575479, 2021). "In summary, these data suggest that the stem-like phenotype of GSCs can be targeted to inhibit tumor growth utilizing negative allosteric inhibitors of Grm3, although monotherapy approaches targeting Grm3 may not suffice to overcome the malignant phenotype of glioblastoma." (PMID 33575479, 2021). "In three of five freshly dissected human glioblastomas, gene expression levels of Grm3 were higher in the CD133-positive GSC population than in CD133-negative non-GSCs, and Grm3 gene expression was overall higher than that of Grm2." (PMID 33575479, 2021). "A novel class of clinically well-tolerated negative allosteric modulators of Grm3 compromised the GSC phenotype, warranting further exploration as anti-glioblastoma agents." (PMID 33575479, 2021).
glioma (9 papers, 2017 to 2024). A benign or malignant brain and spinal cord tumor that arises from glial cells (astrocytes, oligodendrocytes, ependymal cells). "Cross-cancer analyses revealed that gliomas express particularly high levels of Grm3, whereas missense mutations are rare." (PMID 33575479, 2021). "Recent work has demonstrated the pathological significance of the related mGluR3/GRM3 (protein or gene: hGRM3) in gliomas." (PMID 31073373, 2019). "We too were able demonstrated that GRM3 is expressed in glioma cells, that these cells secrete glutamate, and that glutamate in turn activates cell surface GRM3 with resulting downstream activation of the MAPK pathway." (PMID 31073373, 2019). "Given predominant physiologic expression of Grm3 in the brain, high GRM3 expression in gliomas may reflect the tissue of origin of these tumors." (PMID 33575479, 2021). "Single-cell analyses establish preferential expression of Grm3 in glioma stem-like cells (GSCs)." (PMID 33575479, 2021). "Western blot analysis and immunofluorescence was performed to assess for GRM3 expression in commercially available and patient-derived glioma cells and for functional analysis of GRM3 using receptor agonist/antagonists and downstream effectors, ERK and AKT phosphorylation, as the read-out." (PMID 31073373, 2019). "We wanted to confirm that GRM3 was expressed in human glioma cells." (PMID 31073373, 2019). "GRM3 was expressed in most tested glioma samples, and strongly expressed in some." (PMID 31073373, 2019). "We wanted to assess whether GRM3 stimulation by receptor specific agonists in glioma cells could activate two well-known cell proliferation pathways, the MAPK and PI3/AKT pathways." (PMID 31073373, 2019). "The different expression levels of GRM3 and GRM5 in “NT-type” and “NOS-type” was confirmed; however, the difference between low-grade gliomas and GMB was variable and dataset-dependent." (PMID 38509672, 2024).
bipolar disorder (8 papers, 2014 to 2023). A disorder of the brain that causes unusual shifts in mood, energy, activity levels and the ability to carry out day-to-day tasks. "A variant at the position -2 in one isoform of the GRM3 gene (rs148754219) has been considered a risk factor for bipolar disorder." (PMID 37344844, 2023). "GRM3 was reported to be the only genetic marker associated with bipolar disorder." (PMID 33194720, 2020). "Grm3 encodes the glutamate receptor mGluR3, a major regulator of PFC function and cognition, whose disruption leads to working memory defects, as well as development of bipolar disorder." (PMID 29504911, 2018).